PTPN12 (protein tyrosine phosphatase non-receptor type 12)
Diseases named in the same sentence as PTPN12 in open-access papers (continued):
Sharing a sentence is not in itself a finding about the gene and the disease.
tumor (43 papers, 2011 to 2025). "One study found that high PTPN12 staining was associated with cancerous properties that typically lead to poorer prognosis in patients, such as increased lymph node metastasis, tumor cell proliferation, and prostate-specific antigen recurrence." (PMID 34884670, 2021). "Although one member of this family, PTPN12, has been characterized as a negative regulator of growth factor/receptor tyrosine kinase signaling in human BC cells and has been implicated as a tumor suppressors of triple negative BC." (PMID 29590203, 2018). "Further correlation analyses indicated that the decreased expression of PTPN12 was significantly associated with tumor T classification, N classification, distant metastasis, and clinical stage in NPCs (P < 0.05)." (PMID 25663493, 2015). "PTPN12 acts as a negative regulator of multiple RTKs implicated in tumor progression." (PMID 33050232, 2020). "Prior studies have linked several genes (LGALS8, PTPN12, YTHDC2, APOBEC3G, GPX3, RASA3, and TSPAN4) to immune responses, highlighting the impact of the tumor microenvironment (TME) on DCIS." (PMID 41020869, 2025). "PTPN12 modulates the activity of the ATP-dependent ubiquitin separase (p97/Vcp), thereby influencing tumor cell growth and invasion through the regulation of Cas phosphorylation." (PMID 39065585, 2024). "PTPN12, recognized as a tumor suppressor, has received great attention as a promising therapeutic target." (PMID 39065585, 2024). "Validating these findings across various cell lines and cancer types would enhance our understanding of PTPN12’s tumor suppressor role." (PMID 38612874, 2024). "The re-expression of PTPN12 has been demonstrated to attenuate lung metastasis and to impede tumor progression in breast cancer." (PMID 39065585, 2024). "Recent investigations have indicated that PTPN12 exerts its role as a tumor suppressor by regulating various signaling pathways in multiple cancers." (PMID 37333450, 2023). "In recent years, PTPN12 has attracted much attention due to its role in tumor suppression by restraining PTKs." (PMID 37333450, 2023). "MTS and clone formation results showed that PTPN12 overexpression led to marked inhibition of tumor cell proliferation capacity in vitro." (PMID 37333450, 2023). "In bladder cancer, PTPN1 and PTPN12 function as tumor suppressors to attenuate the growth, invasion and migration of cancer cells." (PMID 35957898, 2022). "PTPN12 plays an important regulatory role in tumor deterioration and triple-negative breast cancer (TNBC) transformation." (PMID 35154122, 2022). "The role of PTPN12 in activating anoikis is consistent with its role as a tumor suppressor and also its major effects on adhesion lifetime." (PMID 35927990, 2022). "PTPs have received substantial attention since the discovery of PTPN12, which was described as a tumor suppressor in triple-negative breast cancer." (PMID 34591414, 2021). "In several researches, PTPN12 is characterized as a tumor suppressor which antagonizes EGFR/HER2 signaling, which is contrary to our findings." (PMID 32536826, 2020). "Consistent with this, our data showed that stable knockdown of PTPN12 increased tumor progression in vivo." (PMID 33050232, 2020). "A total of 10,317 (76%) of the 13,660 arrayed tumor samples displayed interpretable PTPN12 staining." (PMID 31606028, 2019). "Several studies have proposed a tumor suppressive role for PTPN12 in various cancers including breast, prostate, colon, kidney, melanoma, and esophageal carcinoma." (PMID 29872503, 2018). "After exclusion of the non-informative samples (unrepresentative samples, samples with too few tumor cells and lost samples), PTPN12 expression was evaluated in a total of 215 (89.6%) patients." (PMID 25868976, 2015). "PTPN12 is one of the PTPs families regulating the equilibrium of tyrosine phosphorylation and plays a prominent role in tumor suppression." (PMID 25663493, 2015).
tumor (continued). "Our findings support the critical role of PTPN12 as a tumor suppressor in the development and progression of NPC." (PMID 25663493, 2015). "Some previous studies have reported that PTPs, including PTPN12, regulate the equilibrium of tyrosine phosphorylation and play a prominent role in tumor suppression." (PMID 25868976, 2015). "We next analyzed clinical features (including AFP level, tumor size, tumor multiplicity, stage and vascular invasion) and PTPN12 expression that displayed significant impact on patient survival based on univariate analyses with Cox proportional hazards model." (PMID 24475046, 2014). "Our current findings support that the critical role of PTPN12 as a tumor suppressor in the development and progression of HCC." (PMID 24475046, 2014). "The results showed that the decreased expression of PTPN12 was negatively correlated with the tumor recurrence (P = 0.005)." (PMID 24475046, 2014). "Further correlation analyses indicated that the decreased PTPN12 expression was closely correlated with tumor recurrence (P = 0.015)." (PMID 24475046, 2014). "Recent data, in tumor contexts, have shown that PTPN12 can dephosphorylate receptor tyrosine kinases." (PMID 23785422, 2013). "Previous studies reported that several PTPs such as PTPN1, PTPN3, and PTPN6 have oncogenic properties but other PTPs including PTPN12 have tumor suppressor features." (PMID 22394684, 2012). "Finally, p27 phosphorylation also increased tumor-initiating stem cell abundance via PTPN12 repression, and Pyk2 driven STAT3 activation in vivo." (PMID 38886396, 2024). "Furthermore, we provided compelling evidence that PTPN12 exerts its tumor suppressor function through the Hippo pathway by suppressing YAP/TAZ-induced increased cell proliferation and migration." (PMID 38612874, 2024). "The tumor-promoting effect of miR146b-3p could be restored by the overexpression of PTPN12 in LSCC cells." (PMID 37333450, 2023). "Conversely, PTPN12 acts as a tumor suppressor gene through the regulation of EGFR expression." (PMID 37333450, 2023). "Collectively, these data indicate that miR-494-3p in sEVs may play a pivotal role in tumor growth, metastasis, and angiogenesis in vivo by targeting PTPN12." (PMID 35136055, 2022). "Finally, PTPN12 inhibits tumor progression in osteosarcoma cells probably by inactivating PI3K/AKT and Erk pathways." (PMID 35957898, 2022). "Immunohistochemical staining revealed that the expression levels of CD-31 and PTPN12 in tumor tissues were significantly increased in the group treated with sEVs, whereas these levels were significantly decreased in the group treated with the miR-494-3p inhibitor." (PMID 35136055, 2022). "PTPN12 has been demonstrated to be a potent tumor suppressor in TNBC and could be a key molecular marker used to predict cancer aggression and patient survival." (PMID 34884670, 2021). "However, we corroborated the tumor-suppressive roles of insertions in Adk and Zbtb20 and in Nipbl, Pdlim5, Ppp1r12a, Tnrc6b, Brd4, Cul3, Ctnna3, Elavl1, Gphn, Nfia, Ptpn12, Taok3, and Rasa1." (PMID 33435458, 2021). "Our results suggest that PTPN12 may phenocopy the tumor suppressor role of PTPRB in murine endothelial cells." (PMID 29872503, 2018). "Since PTPN12 is a frequently inactivated tumor suppressor in several kinds of cancers, our results indicate that PTPN12 inactivation by the selected mutations may play important roles in tumorigenesis in patients." (PMID 29278368, 2017). "PTPN12 also regulates cell migration and cell–cell junctions 14, 15, and serves as an antagonist to tyrosine kinase signaling 16, 17, thereby plays an important role in tumor suppression." (PMID 27075395, 2016).
tumor (continued). "Further correlation analyses showed that the decreased PTPN12 expression was closely correlated with tumor stage, suggesting that PTPN12 might inhibit the differentiation and proliferation of NPC." (PMID 25663493, 2015). "Our findings indicated that PTPN12 might act as a tumor suppressor and serve as a potential predictive biomarker for NSCLC patients, especially for those with non-SCC." (PMID 25868976, 2015). "Most of these findings support the function of PTPN12 as a tumor suppressor." (PMID 25868976, 2015). "These functions implied that PTPN12 play a prominent role in tumor suppression." (PMID 25868976, 2015). "In our study, we demonstrated that decreased PTPN12 expression was closely correlated with tumor recurrence, suggesting that PTPN12 could suppress the formation and proliferation of HCC." (PMID 24475046, 2014). "PTPN12 in particular has been recently shown as a tumor suppressor." (PMID 23240068, 2012). "PTPN12 is known to dephosphorylate oncogenes c-ABL and Src; thus deregulation of PTPN12 might contribute to tumor survival." (PMID 21510904, 2011). "Based on these results, it can be concluded that PTPN12 may function as a tumor suppressor gene." (PMID 37333450, 2023). "Interestingly, PTPN12 acts as a tumor suppressor which regulates the activities of multiple oncogenic tyrosine kinases, including EGFR, human epidermal growth factor receptor 2 (HER2), and platelet-derived growth factor receptor-β (PDGFRβ), and its deficiency is identified in several carcinomas." (PMID 33050232, 2020). "miR-124—a tumor suppressor miRNA—plays a role in cell apoptosis, but in unfavorable conditions, the deregulated expression of miR-124 results in the proliferation of cells by aberrant activation of Kras and Akt pathways through the negative regulation of PTPN12." (PMID 33490232, 2020). "Therefore, we assessed other RTK downstream effector pathways that could be targets for PTPN12-mediated regulation driving tumor growth." (PMID 29872503, 2018). "PTPN12 is a key regulator of integrin-mediated adhesion and migration of endothelial cells by dephosphorylating the cytoskeleton regulators Cas, paxillin, and Pyk2, such an activity likely explains the critical role of PTPN12 in vascular development and tumor formation." (PMID 25663493, 2015). "Overall, the effect of PTPN12, IDH2, P2RX4, and KDELR2 on tumor immune cell infiltration is a complex process that typically involves multiple molecular pathways and signaling pathways." (PMID 37563735, 2023). "This study provides the first description of the expression and clinical significance of PTPN12 in LSCC and provides evidence suggesting that PTPN12 functions as a tumor suppressor in the development and progression of LSCC." (PMID 37333450, 2023). "In contrast, the miR-494-3p inhibitor significantly downregulated the expression of PTPN12 and suppressed tumor growth and angiogenesis, confirming that miR-494-3p in sEVs could significantly increase sEV-mediated cell–cell communication to induce malignant tumor progression in the TME." (PMID 35136055, 2022). "The literature mentioned that PTPN12, a kind of phosphatase, dephosphorylates FAK, thus reducing the number of focal contacts and consequently increasing tumor cell migration and invasion." (PMID 34336845, 2021). "Further building upon in vitro data, in vivo experiments conducted in NOD/SCID mice indicated that restoring PTPN12 expression in orthotopically transplanted TNBC, via a dox-inducible model, decreased tumor progression and metastasis to the lungs." (PMID 34884670, 2021). "We demonstrated that CD99 activation regulates actin cytoskeleton dynamics through PTPN12/FAK/Rho/Rac axis, thereby suppressing EGFR activation and relevant tumor growth." (PMID 33050232, 2020).
tumor (continued). "To determine the anti-tumorigenic effect of CD99CRIII3 and the importance of PTPN12 in suppressing tumor progression, we generated a stable MDA-MB-231 cell line (shPTPN12-MDA-MB-231) with 75% reduction in PTPN12 protein using the shRNA system." (PMID 33050232, 2020). "Serial sections of the tumor specimens were stained with hematoxylin and eosin (H&E) and antibodies to measure the expression of Ki67, EGFR, and PTPN12." (PMID 33050232, 2020). "Scenario 3 was a mix of pre- and postoperative parameters (PTPN12 staining, preoperative serum PSA, clinical tumor stage (cT) and the prostatectomy Gleason grade)." (PMID 31606028, 2019). "We observed that the expression of Protein Tyrosine Phosphatase Non-Receptor Type 12 (PTPN12), an important phosphatase which enables increased focal adhesions as well as inhibits tumor growth, was significantly down-regulated at 0 h." (PMID 31477016, 2019). "Protein tyrosine phosphatase non-receptor type 12 (PTPN12), has been identified as a potent tumor suppressor in human cancers and a critical regulator of cell adhesion and migration." (PMID 24475046, 2014). "We, therefore, estimated the roles of classical PTPs in anti-PD-L1 treatment and found that seven PTPs were significantly higher in the non-responsive tumor, including PTPN12 and PTPRE." (PMID 36341348, 2022). "In clear cell renal cell carcinoma, PTPN3 and PTPN13 act as tumor suppressors by inactivating the AKT signaling pathway, whereas PTPN12 restrains the proliferation of renal cell carcinoma by inhibiting PI3K/mechanistic target of rapamycin (mTOR) pathway activity." (PMID 35957898, 2022). "The protein tyrosine phosphatase non-receptor type 12 (PTPN12) has been known as a tumor suppressor in TNBC." (PMID 34207383, 2021). "Although several studies imply the functional significance of PTPN12 in controlling tumor progression, the activator of PTPN12 has not been identified yet." (PMID 33050232, 2020). "PTPN12 is a tumor suppressor which regulates cellular transformation from normal to malignant cells via the inhibition of multiple oncogenic tyrosine kinases." (PMID 33050232, 2020). "This revealed a tighter relationship of high PTPN12 staining levels with unfavorable tumor features in ERG negative than in ERG positive cancers." (PMID 31606028, 2019). "Protein tyrosine phosphatase non-receptor 12 (PTPN12) is ubiquitously tyrosine phosphatase with tumor suppressive properties." (PMID 31606028, 2019). "Moreover, expression of some PTP tumor suppressors, such as PTPRD, PTPRO, PTPN12, PTPN13 and DUSP1, is reduced due to epigenetic silencing." (PMID 29558404, 2018). "Our results suggest that the decreased PTPN12 expression in HCC may facilitate an increased malignant feature and/or a worse survival in this tumor type." (PMID 24475046, 2014). "Classical protein tyrosine phosphatase nonreceptor type 12 (PTPN12) has been extensively studied to decipher its mechanism as a tumor suppressor gene in various human carcinomas; however, there is no comprehensive elucidation of the PTPN12 expression and its regulatory mechanisms in LSCC." (PMID 37333450, 2023). "Furthermore, PTPN3, PTPN6, PTPN12 and PTPN13 play tumor suppressor roles in lung cancer." (PMID 35957898, 2022). "CD99 acts as an upstream regulator of the PTPN12-mediated negative feedback loop for regulating ligand-induced dimerization or oligomerization of plasma membrane protein kinases, which are involved in tumor development and progression." (PMID 33050232, 2020). "We found that decreased PTPN12 expression was a prognostic factor for poor cancer-specific survival and recurrence-free survival of HCC patients (P<0.001) independent of serum AFP levels, tumor size, multiplicity, clinical stage and vascular invasion as evidenced by multivariate analysis." (PMID 24475046, 2014).
cancer (36 papers, 2011 to 2025). A tumor composed of atypical neoplastic, often pleomorphic cells that invade other tissues. "Several genes of considerable intrigue, such as LRRFIP1 and PTPN12, are repeatedly associated with transcription regulation and cancer-related pathways." (PMID 39684787, 2024). "Univariate analysis showed a significant association between decreased expression of PTPN12 and adverse cancer-specific survival and recurrence-free survival (P<0.001)." (PMID 24475046, 2014). "Although the correlation of PTPN12 expression in cancer and patient survival has been the focus of various studies, the underlying mechanism by which PTPN12 affects prognosis remains elusive and will require future investigation." (PMID 24475046, 2014). "Understanding the underlying molecular mechanism of the Hippo pathway regulation by PTPN12 may provide information about targeting oncogenes that are overactivated upon the loss of PTPN12 in cancer treatment." (PMID 38612874, 2024). "A major tyrosine phosphatase that was implicated in cancer and motility was PTPN12." (PMID 35927990, 2022). "Moreover, it is well possible that the causes and consequences of PTPN12 overexpression differ between different cancer types." (PMID 31606028, 2019). "PTPN12 variants, such as Ile322 and Ala573, might be involved in regulating phosphatase activity and then be meaningful for human cancer." (PMID 27075395, 2016). "Given PTPN12’s involvement in other cancer types, further exploration of its interactions with the Hippo pathway in diverse cancers is warranted." (PMID 38612874, 2024). "Taken together, these data support a model in PI3K-activated cancers, in which C-terminally phosphorylated p27 activates T-ISC expansion or maintenance though p27/STAT3/cJun-dependent PTPN12 loss and activation of Pyk2 and STAT3." (PMID 38886396, 2024). "We also observed that PTPN12 was positively correlative with most immunomodulators across cancer types." (PMID 36341348, 2022). "miR-494-3p was abundant in Ras- and syntenin-1-dependent sEVs and mediated sEV-induced migration and invasion of cancer cells and angiogenesis by targeting PTPN12 in the TME." (PMID 35136055, 2022). "Overall, SHP-2 seems to be a relatively well-studied phosphatase with a similar function across many cell types, whereas PTPN12 and cPAcP are emerging PTPs that require further studies to elucidate their role in other cancers." (PMID 34884670, 2021). "In triple-negative breast cancer (TNBC) with loss of PTPN12, treatments using a combination of RTK inhibitors are effective in mediating cell death, including in chemorefractory cancers." (PMID 33411917, 2021). "Other PTPs, such as SHP-1 and PTPN12, have acquired some information as to how they modulate cancer progression but require further research owing to their differing mechanisms in different cancers." (PMID 34884670, 2021). "Approximately 300 co-clustering phosphosites are verified in patient samples of 5 cancer types or previously implicated in cancer, including CTNNB1 p.S29/Y30, EGFR p.S720, MAPK1 p.S142, and PTPN12 p.S275." (PMID 33875650, 2021). "All of these indicate that functions of PTPN12 are different in various cancer types, and comprehensive studies are required to clarify its specific mechanisms." (PMID 32536826, 2020). "Several of these genes play a particular role in the growth controlling EGFR-pathway, which fits well to the markedly elevated Ki67 LI in cancers with high PTPN12 expression." (PMID 31606028, 2019). "It is well conceivable that differences in the cellular microenvironment with more than 1600 dysregulated genes in ERG activated cancers impact the biological effect of molecular features such as PTPN12." (PMID 31606028, 2019). "Collectively, these data suggest that PTPN12 plays an important role in disease progression in a variety of cancers." (PMID 29872503, 2018).